PSMB11 (proteasome subunit beta 11)
Description:
The proteasome is a multicatalytic proteinase complex which is characterized by its ability to cleave peptides with Arg, Phe, Tyr, Leu, and Glu adjacent to the leaving group at neutral or slightly basic pH. The proteasome has an ATP-dependent proteolytic activity. Incorporated instead of PSMB5 or PSMB8, this unit reduces the chymotrypsin-like activity of the proteasome (By similarity). Plays a pivotal role in development of CD8-positive T cells (By similarity).
Synonyms: beta5t
Tractability: Small molecule: an approved drug acts on it; a high-quality ligand is known; it belongs to a druggable protein family. PROTAC: a small molecule that binds it is known.
Gene: Protein-coding gene on chromosome 14 (23,042,212 to 23,044,060, forward strand). Ensembl gene ENSG00000222028.
Subcellular location: Cytoplasm; Nucleus
Pathways (Reactome):
Metabolism of proteins: Proteasome assembly
Gene Ontology:
Molecular function: peptidase activity; protein binding; endopeptidase activity; threonine-type endopeptidase activity
Biological process: proteolysis; CD8-positive, alpha-beta T cell differentiation; CD8-positive, alpha-beta T cell homeostasis; proteasomal protein catabolic process; proteasome-mediated ubiquitin-dependent protein catabolic process; thymic T cell selection; protein catabolic process
Cellular component: cytosol; nucleus; proteasome complex; proteasome core complex, beta-subunit complex; cytoplasm; proteasome core complex
Genetic constraint (gnomAD): Loss-of-function variants: 3 observed, 0.64 expected, observed/expected ratio (o/e) 4.69. That is too few expected variants to judge how well the gene tolerates losing a copy. Missense variants: 411 observed, 423.04 expected, observed/expected ratio (o/e) 0.97, 90% interval 0.89 to 1.05. Synonymous variants: 163 observed, 174.48 expected, observed/expected ratio (o/e) 0.93, 90% interval 0.82 to 1.06.
Homologues: Orthologues: rabbit PSMB11 (87% identical), mouse Psmb11 (83% identical), rat Psmb11 (82% identical), pig PSMB11 (81% identical), dog PSMB11 (79% identical), guinea pig PSMB11 (79% identical), macaque PSMB11 (69% identical), zebrafish psmb11b (47% identical), zebrafish psmb11a (42% identical), tropical clawed frog psmb11 (40% identical), Drosophila melanogaster Prosbeta1 (19% identical), Caenorhabditis elegans pbs-1 (18% identical). Paralogues in human: PSMB8 (42% identical), PSMB5 (39% identical), PSMB6 (23% identical), PSMB7 (22% identical), PSMB10 (20% identical), PSMB9 (20% identical), PSMB1 (17% identical), PSMB4 (16% identical), PSMB3 (15% identical), PSMA4 (15% identical), PSMA1 (14% identical), PSMB2 (14% identical), and 6 more.
Diseases named in the same sentence as PSMB11 in open-access papers:
PSMB11 is named in the same sentence as 3 diseases in open-access papers, as found by Europe PMC text mining. Sharing a sentence is not in itself a finding about the gene and the disease. The quoted sentences say what the papers report.
thymoma (1 paper, 2020). A neoplasm arising from the epithelial cells of the thymus. "PSMB11 displayed an increasing expression along with enhanced involvement of the type B thymoma component." (PMID 31967407, 2020). "CNOT2, CNOT9, CD99, PRSS16, PSMB11, and SHMT1 were found with high abundance in thymoma and participated mainly in nucleic acid and amino acid metabolism." (PMID 31967407, 2020). "Recently, WHO had suggested a dozen of histochemical markers to differentiate type A and type B thymoma, including TdT, CD1a, CD99, PSMB11 (Beta5T), PRSS16, Cathepsin V, and desmin." (PMID 31967407, 2020). "Compared with conventional subtyping markers (e.g., TdT, PRSS16, and PSMB11), CNOT2/9 and SHMT1 not only exhibited good segregating capabilities for thymoma and TSCC, but also showed great prognosis indicating potentials." (PMID 31967407, 2020).
cancer (3 papers, 2018 to 2024). A tumor composed of atypical neoplastic, often pleomorphic cells that invade other tissues. "However, PSMB11 expression was only weakly correlated with a few cancer types." (PMID 39127727, 2024). "In comparison with the other PSM genes, differential expression of PSMB11 was relatively uncommon, whereas PSME3 and PSMG3 were found to be differentially expressed in virtually all examined cancer forms (15/16 cancer types)." (PMID 36123629, 2022). "Furthermore, co-amplification of PSM genes located in close proximity to one another (e.g. PSMB5 and PSMB11, 14q11.2; PSMB4 and PSMD4, 1q21.3; PSMB8 and PSMB9, 6p21.32) or known cancer drivers (e.g. co-amplification of ERBB2 and PSMB3) were also frequently amplified together." (PMID 36123629, 2022).
PSMB11 also shares sentences with these, for which no sentence is quoted: viral infection (1 paper).